ZNF692 (zinc finger protein 692)
Description:
May act as an transcriptional repressor for PCK1 gene expression, in turn may participate in the hepatic gluconeogenesis regulation through the activated AMPK signaling pathway.
Synonyms: AREBP; ZFP692; FLJ20531
Tractability: Small molecule: a structure with a bound ligand is known. PROTAC: ubiquitination databases record sites on it.
Gene: Protein-coding gene on chromosome 1 (248,850,004 to 248,859,144, reverse strand). Ensembl gene ENSG00000171163.
Subcellular location: Nucleus
Subcellular location (Human Protein Atlas): Nucleoli; Nucleoplasm
Pathways (Reactome):
Gene expression (Transcription): Generic Transcription Pathway
Gene Ontology:
Molecular function: DNA-binding transcription repressor activity, RNA polymerase II-specific; protein binding; RNA polymerase II cis-regulatory region sequence-specific DNA binding; DNA-binding transcription factor activity
Biological process: negative regulation of transcription by RNA polymerase II; regulation of gluconeogenesis; regulation of transcription by RNA polymerase II
Cellular component: nucleolus; nucleoplasm; nucleus
Genetic constraint (gnomAD): Loss-of-function variants: 43 observed, 50.01 expected, observed/expected ratio (o/e) 0.86, 90% interval 0.67 to 1.11. The upper end of that interval is the gene's LOEUF score, 1.11, which puts it in group 4 of 6, group 1 being the genes least tolerant of losing a copy. Missense variants: 662 observed, 674.62 expected, observed/expected ratio (o/e) 0.98, 90% interval 0.92 to 1.05. Synonymous variants: 288 observed, 251.71 expected, observed/expected ratio (o/e) 1.14, 90% interval 1.04 to 1.26.
Homologues: Orthologues: chimpanzee ZNF692 (99% identical), macaque ZNF692 (98% identical), pig ZNF692 (85% identical), rat Zfp692 (78% identical), mouse Zfp692 (76% identical), dog ZNF692 (75% identical), rabbit ZNF692 (70% identical), guinea pig ZNF692 (69% identical). Paralogues in human: ZFP91 (28% identical), ZNF653 (23% identical), ZNF276 (23% identical), PRDM1 (14% identical), ZBTB20 (14% identical), ZNF451 (14% identical), PATZ1 (14% identical), ZNF76 (13% identical), PRDM10 (13% identical), ZNF143 (13% identical), HIC1 (13% identical), ZNF410 (13% identical), and 24 more.
Diseases named in the same sentence as ZNF692 in open-access papers:
ZNF692 is named in the same sentence as 19 diseases in open-access papers, as found by Europe PMC text mining. Sharing a sentence is not in itself a finding about the gene and the disease. The quoted sentences say what the papers report.
colon adenocarcinoma (6 papers, 2021 to 2024). "ZNF692 expression was shown to be significantly associated with tumor stage and metastasis in colon adenocarcinoma (COAD)." (PMID 38650011, 2024). "ZNF692 has been shown to promote cell proliferation in cancers such as lung adenocarcinoma, colon adenocarcinoma, and clear cell renal carcinoma." (PMID 38453820, 2024). "ZNF692 emerges as a novel oncogene and a promising therapeutic target for individuals diagnosed with colon adenocarcinoma (COAD)." (PMID 37980166, 2023). "ZNF692, also known as AREBP and Zfp692, was reported to have an important role in cell proliferation, invasion, and metastasis of lung and colon adenocarcinomas." (PMID 35281811, 2022). "ZNF692 promotes cell proliferation, migration, and invasion in colon adenocarcinoma (COAD) by downregulating p27kip1 or upregulating cyclin D1, cyclin-dependent kinase 2 (CDK2), matrix metalloproteinase-9 (MMP-9), and PI3K/Akt signaling." (PMID 36358661, 2022). "For example, ZNF692 promotes in vitro colon adenocarcinoma (COAD) cell proliferation, migration, and invasion by activating the PI3K/AKT signaling pathway, and high ZNF692 expression is significantly correlated with tumor metastasis in patients with COAD." (PMID 38453820, 2024). "For instance, CIZ1, ZNF217, ZNF281, ZKSCAN3, ZNF692, ZNF750, and ZFP36 proteins are closely related to the tumor volume, lymph node metastasis status, and TNM stage, and their expression levels had statistically significant effects on the survival time of patients with colon adenocarcinoma." (PMID 36358661, 2022).
cervical cancer (5 papers, 2022 to 2024). A primary or metastatic malignant neoplasm involving the cervix. "ZNF692 is linked to the recurrence of Wilms’ tumor, and promotes the proliferation and invasion of cervical cancer cells." (PMID 38735008, 2024). "ZNF692 was upregulated in cervical cancer tissues, and its overexpression was associated with poor clinicopathological characteristics in patients with cervical cancer." (PMID 35281811, 2022). "ZNF692 overexpression in cervical cancer is linked to unfavorable clinicopathological features." (PMID 38650011, 2024). "ZNF692 conduces to the malignant phenotypes (proliferation, migration, and invasion) of cervical cancer cells by suppressing p27kip1 transcription." (PMID 38453820, 2024). "Functional investigations have shown that ZNF692 regulates the proliferation and invasion of cervical cancer cells by suppressing the transcription of p27kip1." (PMID 38650011, 2024). "Currently, the roles of ZNF692 have been documented exclusively in lung, colon, and cervical cancers." (PMID 37980166, 2023). "Recent reports have shown that ZNF692 is linked to the recurrence of Wilms’ tumor, the prognosis and proliferation of ccRCC, and the aggressiveness of lung adenocarcinoma (LUAD) and that it promotes the proliferation and invasion of cervical cancer cells." (PMID 38735008, 2024). "ZNF692 displayed promise as a therapeutic target and prognostic marker for cervical cancer (CC)." (PMID 37980166, 2023). "Despite the results revealed ZNF692 exhibited tumor-promoting activity in malignancies like LUAD, COAD, and cervical cancer, its significance and precise mechanism in osteosarcoma still has not been clarified untill now." (PMID 38650011, 2024).
osteosarcoma (5 papers, 2022 to 2024). A usually aggressive malignant bone-forming mesenchymal neoplasm, predominantly affecting adolescents and young adults. "Collectively, our data demonstrate that ZNF692 is elevated in osteosarcoma and is associated with a worse outcome in individuals with osteosarcoma." (PMID 38650011, 2024). "Our study revealed that ZNF692 was a potential risk factor in osteosarcoma in both univariate and multivariate Cox regression models, irrespective of clinical features such as gender and age." (PMID 38650011, 2024). "High expression of ZNF692 is associated with poor overall survival in patients with lung adenocarcinoma, osteosarcoma, or bladder cancer." (PMID 38453820, 2024). "The Kaplan–Meier survival analysis suggested that lower expressions of ATMIN, ZNF438, and ZNF597 and the higher expression of ZNF692 were associated with worse overall survival in osteosarcoma." (PMID 35281811, 2022). "Therefore, ZNF692 might function as a risk factor and an independent prognostic biomarker in osteosarcoma." (PMID 38650011, 2024). "Overall, our findings suggest that ZNF692 enhances the proliferation, migration, and invasion of osteosarcoma cells in vitro." (PMID 38650011, 2024). "ZNF692 enhances the proliferation, migration, and invasion of osteosarcoma cells via TNK2-dependent stimulation of the MEK/ERK signaling pathway." (PMID 38650011, 2024). "We investigated the dysregulation and clinical significance of ZNF692 in osteosarcoma through bioinformatic method and experimental validation." (PMID 38650011, 2024). "Increased expression of ZNF692 is a reliable predictor of worse overall survival in osteosarcoma patients." (PMID 38650011, 2024). "In order to investigate the impact of ZNF692 on the malignant behavior of osteosarcoma cells, we assessed the influence of ZNF692 overexpression on the proliferation, migration, and invasion of these cells." (PMID 38650011, 2024). "U0126, a potent inhibitor specifically targeting the MEK/ERK signaling pathway, partially counteracts the impact of ZNF692 overexpression on the proliferation, migration, and invasion of osteosarcoma cells." (PMID 38650011, 2024). "The results from wound-healing and transwell invasion studies demonstrated enhanced cell migration and invasion in osteosarcoma cells that had a stable overexpression of ZNF692." (PMID 38650011, 2024). "Here, our investigation reveals a consistent up-regulation of ZNF692 in osteosarcoma, and establishes a noteworthy correlation between elevated ZNF692 expression and worse clinical prognosis in osteosarcoma patients." (PMID 38650011, 2024). "Collectively, our findings indicate that ZNF692 enhances the proliferation, migration, and invasion of osteosarcoma cells by activating the MEK/ERK pathway via TNK2." (PMID 38650011, 2024). "We subsequently assessed the expression of ZNF692 in osteosarcoma tissues using Western blot and qRT-PCR." (PMID 38650011, 2024). "ZNF692 promotes proliferation, migration and invasion of osteosarcoma cells through TNK2-mediated MEK/ERK pathway activation." (PMID 39717098, 2024). "Downregulation of ZNF692 inhibits the proliferation, migration, and invasion of osteosarcoma cells, whereas upregulation of ZNF692 has the opposite impact." (PMID 38650011, 2024). "In order to examine the impact of ZNF692 on the proliferation of osteosarcoma cells in vivo, we subcutaneously injected 143B cells that had been genetically modified to suppress ZNF692, as well as control cells, into nude mice." (PMID 38650011, 2024). "The use of luciferase reporter assay and ChIP assay provides confirmation that ZNF692 increases the transcription of TNK2 in osteosarcoma cells through binding to the promotor region." (PMID 38650011, 2024). "Subsequently, CCK-8, colony formation, and Edu incorporation assays were used to investigate the impact of ZNF692 silencing on the proliferation of osteosarcoma cells." (PMID 38650011, 2024).
osteosarcoma (continued). "Initially, we discovered that ZNF692 exhibited an increase in expression in osteosarcoma tissues and cell lines." (PMID 38650011, 2024). "In the same way, the inhibition of TNK2 in osteosarcoma cells partly counteracted the enhancing impact of ZNF692 overexpression on P-MEK1/2 and P-ERK1/2." (PMID 38650011, 2024). "The findings indicate that ZNF692 has a favorable regulatory effect on the MEK/ERK signaling pathway in osteosarcoma cells." (PMID 38650011, 2024). "In order to provide further evidence for the role of ZNF692-mediated MEK/ERK signaling in promoting osteosarcoma cell proliferation, migration, and invasion, we used U0126, a highly specific inhibitor of MEK/ERK signaling." (PMID 38650011, 2024). "ZNF692 promotes the proliferation, migration, and invasion of osteosarcoma cells via the TNK2-dependent stimulation of the MEK/ERK signaling pathway." (PMID 38650011, 2024). "Similarly, downregulation of ZNF692 in a transwell invasion assay greatly hindered the invasion of osteosarcoma cells." (PMID 38650011, 2024). "Recently, zinc was shown to promote apoptosis in osteosarcoma cells, while zinc-related proteins such as zinc finger protein 692 (ZNP692) could increase osteosarcoma cell proliferation and migration." (PMID 38998445, 2024). "Furthermore, the levels of ZNF692 expression were significantly elevated in osteosarcoma cell lines (HOS, MG63, U2OS, 143B, and Saos-2) compared to human osteoblast cells (FOB1.19)." (PMID 38650011, 2024). "Thus, we investigated the potential impact of ZNF692 knockdown on cellular proliferation, migration, and invasion in osteosarcoma cells." (PMID 38650011, 2024). "Expression of ZNF692 was increased in both human osteosarcoma tissues and cell lines." (PMID 38650011, 2024). "In conclusion, our investigation elucidated the pro-tumorigenic function of ZNF692 in osteosarcoma." (PMID 38650011, 2024). "Besides, a strong correlation was seen between elevated levels of ZNF692 and worse prognosis in individuals diagnosed with osteosarcoma." (PMID 38650011, 2024). "Thus, our research reveals that ZNF692 is a potentially new prognostic predictor and an oncogenic factor osteosarcoma." (PMID 38650011, 2024). "Furthermore, the expression of ZNF692 served as an independent predictive biomarker in osteosarcoma." (PMID 38650011, 2024). "In order to better understand the molecular mechanism behind the ZNF692-mediated increase in osteosarcoma cell proliferation, migration, and invasion, we conducted Pearson’s correlation analysis on the TCGA osteosarcoma expression matrix to identify the genes related with ZNF692." (PMID 38650011, 2024). "We further examine the prognostic predictive capability of ZNF692 in osteosarcoma." (PMID 38650011, 2024). "In addition, we discovered that U0126, a small molecule inhibitor of MEK/ERK signaling, partially counteracted the impacts of ZNF692 overexpression on the proliferation, migration, and invasion of osteosarcoma cells." (PMID 38650011, 2024). "Functional experiments indicates that ZNF692 has a tumor-promoting function in osteosarcoma." (PMID 38650011, 2024). "Additionally, overexpression of ZNF692 stimulates the proliferation, migration, and invasion of osteosarcoma cells." (PMID 38650011, 2024). "Our work demonstrated that ZNF692 functions as an oncogene in osteosarcoma." (PMID 38650011, 2024). "In summary, our research reveals that ZNF692 may serve as a novel prognostic indicator and oncogene in osteosarcoma." (PMID 38650011, 2024). "ZNF692 might play a role as a potential predictive biomarker and a promising target for novel therapeutics in osteosarcoma in the future." (PMID 38650011, 2024). "Thus, it may be inferred that ZNF692 enhances the proliferation, migration, and invasion of osteosarcoma cells by stimulating the MEK/ERK signaling pathway." (PMID 38650011, 2024). "Therefore, it is reasonable to speculate that ZNF692 might have an effect on the malignant behaviors of osteosarcoma cells." (PMID 35281811, 2022).
osteosarcoma (continued). "In order to investigate the involvement of TNK2 in the activation of the MEK/ERK signaling pathway by ZNF692, we altered the expression of TNK2 in osteosarcoma cells with either reduced or increased levels of ZNF692." (PMID 38650011, 2024). "We created a composite panel by integrating ZNF692 and TNK2 to forecast the prognosis of osteosarcoma." (PMID 38650011, 2024). "Regarding osteosarcoma, our analysis of the GSE126209 dataset from the GEO database revealed a significant upregulation of ZNF692 expression in tumor tissues compared to normal tissues." (PMID 38650011, 2024). "In addition, ZNF692 specifically interacts with the promoter region of TNK2 and stimulates the transcription of TNK2 in osteosarcoma cells." (PMID 38650011, 2024). "Collectively, our findings indicate that the absence of ZNF692 inhibits the proliferation, migration, and invasion of osteosarcoma cells." (PMID 38650011, 2024).
bladder cancer (2 papers, 2020 to 2024). "We downloaded another online data set, GSE19915, which included 144 bladder cancer patients to test the prognostic performance of these genes, but only three genes (CORO1C, TMPRSS4, and ZNF692) could match the probes in later survival analysis." (PMID 32695668, 2020).
hepatocellular carcinoma (2 papers, 2023 to 2024). A malignant tumor that arises from hepatocytes. "We constructed a competing endogenous RNA (ceRNA) network involving AC009403.11/miR-126-3p/ZNF692 in hepatocellular carcinoma (HCC)." (PMID 37980166, 2023).
lung adenocarcinoma (2 papers, 2024). A carcinoma that arises from the lung and is characterized by the presence of malignant glandular epithelial cells. "ZNF692 also contributes to the proliferation, migration, and invasion of lung adenocarcinoma cells and inhibits their apoptosis." (PMID 38453820, 2024). "For instance, the excessive expression of ZNF692 was shown to be an independent risk factor for worse overall survival in lung adenocarcinoma (LUAD), and in vitro and in vivo experiments indicated that suppressing ZNF692 hindered cell proliferation, migration, and invasion of LUAD cells." (PMID 38650011, 2024). "Moreover, ZNF692 highly correlates with genes involved in the regulation of metabolic process in lung adenocarcinoma." (PMID 38453820, 2024).
prostate carcinoma (2 papers, 2021 to 2024). A carcinoma that arises from epithelial cells of the prostate gland. "Transwell assay and scratch assay showed reduced invasion and migration of prostate cancer PC3 cells that knocked out ZNF692." (PMID 38291502, 2024). "CCK8 and Edu results showed that the proliferation of prostate cancer PC3 cells that knocked down ZNF692 was slowed." (PMID 38291502, 2024). "Future studies are needed to explore in detail how ZNF692 interacts with these signaling pathways and other potentially relevant factors, and how these interactions contribute to prostate cancer aggressiveness, migration, treatment resistance, and recurrence." (PMID 38291502, 2024). "Flow cytometry showed that the apoptosis rate of prostate cancer PC3 cells after ZNF692 knockout was increased." (PMID 38291502, 2024). "At the cellular level, ZNF692 was overexpressed to varying degrees in prostate cancer cell lines, with the highest expression in PC3 cell lines." (PMID 38291502, 2024). "The state of prostate cancer PC3 cells that overexpressed ZNF692 was reversed from the state after ZNF692 was knocked down." (PMID 38291502, 2024). "PC3 cells were selected to construct the ZNF692 knockout prostate cancer cell line." (PMID 38291502, 2024). "ZNF692 is overexpressed in many tumors, and the high expression of ZNF692 is correlated with tumor aggressiveness and tumor phenotype of prostate cancer, suggesting that ZNF692 may play an important role in tumor biology of prostate cancer." (PMID 38291502, 2024). "In summary, our results suggest that ZNF692 upregulates c-Myc and CyclinA1 by activating EMT signaling pathway, promotes the proliferation and resistance to apoptosis of prostate cancer cells, and enhances cell invasion and migration." (PMID 38291502, 2024). "The expression of ZNF692 in normal prostate cells (RWPE-1) and three prostate cancer cells (PC3, DU145, LNCaP) was analyzed by qRCR." (PMID 38291502, 2024). "The expression level of ZNF692 was verified in normal prostate cells (RWPE-1) and prostate cancer cells (LNCaP, PC3, DU145)." (PMID 38291502, 2024). "However, although our study sheds light on the role of ZNF692 in EMT processes and prostate cancer progression, the detailed molecular mechanisms still require further investigation." (PMID 38291502, 2024).
lentivirus infection (1 paper, 2024). Virus diseases caused by the Lentivirus genus. "Initially, we suppressed the expression of ZNF692 in 143B and U2OS cells using lentivirus infection." (PMID 38650011, 2024).
pan (1 paper, 2023). "In summary, the potential of ZNF692 as a diagnostic and prognostic indicator in pan cancer is noteworthy." (PMID 37980166, 2023). "In this study, we investigated the association between the expression of ZNF692 and various factors including stage, MSI, and TMB in pan cancer." (PMID 37980166, 2023). "Consequently, this study aimed to investigate the potential role of ZNF692 in pan cancer." (PMID 37980166, 2023). "No genetic alterations of ZNF692 have been reported in pan cancer." (PMID 37980166, 2023).